TLR4 (toll like receptor 4)
Diseases named in the same sentence as TLR4 in open-access papers (continued):
Sharing a sentence is not in itself a finding about the gene and the disease.
multiple sclerosis (28 papers, 2013 to 2025). A progressive autoimmune disorder affecting the central nervous system resulting in demyelination. "The ENV protein of the MSRV virus, which is HERV-W associated with multiple sclerosis, acts as a strong agonist of toll-like receptor 4 (TLR-4), a pattern recognition receptor in innate immunity, triggering an inflammatory response." (PMID 39857643, 2024). "For example, the Env protein of HERV-W has been confirmed to induce inflammation in patients with multiple sclerosis through the toll-like receptor 4 (TLR4) activation pathway." (PMID 35359739, 2022). "Activation of GABAB receptors downregulated TLR4-induced NF-κBp65 nuclear expression and proinflammatory cytokine release in mixed glia in a multiple sclerosis (MS) model." (PMID 30647535, 2018). "Activation of GABAB receptors downregulated TLR4-induced NF-κBp65 nuclear expression and release of proinflammatory cytokines in mixed glia of a multiple sclerosis (MS) model." (PMID 30647535, 2018). "In the present study, we evaluated the immunomodulatory effect of murine MSCs after treatment with TLR3 and TLR4 agonists in vitro and in a mouse model of multiple sclerosis." (PMID 27724984, 2016). "TLR4 is a component of the NFkB pathway leading to cytokine production, and in this regard, this receptor induces demyelination and inflammation, as shown in diseases like multiple sclerosis." (PMID 38672445, 2024). "In one of the most investigated groups, the HERV-W, the Env surface subunit has been characterized to be a potent stimulator of TLR4, harboring remarkable pro-inflammatory properties that might contribute to multiple sclerosis immunopathogenesis." (PMID 30250470, 2018). "In multiple sclerosis, sCD14 was suggested to be an antagonist of TLR-4 signaling at low concentrations but could promote pro-inflammatory cytokines release at high concentrations." (PMID 24098711, 2013). "Expression of Syncytin-1 outside the placenta has been reported, capable of activating a pro-inflammatory and autoimmune cascade through receptors CD14 and TLR4 (Toll-Like Receptor 4) on antigen-presenting cells, and also of triggering dysregulation of T-lymphocytes in multiple sclerosis (MS)." (PMID 24098463, 2013). "ApTOLL is an aptamer selected to antagonize Toll-like receptor 4 (TLR4), which is involved in immunological and inflammatory reactions in demyelinating diseases like multiple sclerosis (MS) and autoimmune encephalomyelitis (EAE)." (PMID 41012445, 2025). "In multiple sclerosis, S100A4 overexpression promotes microglial polarization of pro-inflammatory type via the TLR4/NF-κB pathway, initiating neuroinflammation." (PMID 40787447, 2025). "Toll-like receptor 4 (TLR4) is well known for activating the innate immune system; however, it is also highly expressed in adaptive immune cells, such as CD4+ T-helper 17 (Th17) cells, which play a key role in multiple sclerosis (MS) pathology." (PMID 31561751, 2019). "LPS is a TLR4 agonist that activates microglia and alters the levels of MAPKs, NF-κB, iNOS, COX-2, PGE-2, proinflammatory cytokines, nitrites, and reactive oxygen species, which are involved in various neurodegenerative diseases such as AD, PD, and multiple sclerosis (MS)." (PMID 28671636, 2017).
periodontal disease (28 papers, 2013 to 2026). "The contribution of TLR4 in periodontal disease appears to be complex, as it was reported in a separate study that TLR4 participates in P. gingivalis-elicited oral bone loss." (PMID 29621153, 2018). "In a cohort of Chinese individuals, a TLR4 polymorphism distinguished moderate from severe periodontal disease." (PMID 29621153, 2018). "These elements may have influenced the composition of the oral microbiota and the clinical manifestation of periodontal disease, thereby affecting the interpretation of the association with TLR4 gene polymorphisms." (PMID 40552316, 2025). "Although both TLR2 and TLR4 have been implicated in periodontal disease progression, various studies utilizing knockout mice and in vitro systems suggest that TLR2 plays the most direct role is in sensing various components produced by periodontal pathogens that drive alveolar bone destruction." (PMID 34255809, 2021). "The present study also provides in vivo evidence that Pg-LPS can inhibit TLR4-mediated increases in blood levels of IL-10, a cytokine thought to prevent the development of periodontal disease." (PMID 38857232, 2024). "A number of candidate gene studies showed that IL1A, IL1B, IL4, IL6, IL10, TNFA, FcγR, VDR, TLR2, TLR4, and MMP1 were the main genes associated with periodontal disease." (PMID 36294882, 2022). "We measured the level of LBP in the mice serum in order to detect another potential route of periodontal disease (HFD gut dysbiosis-LPS/TLR4 pathway-gingival blood flow-periodontal disease)." (PMID 33746772, 2021). "In order to make the most meaningful comparison of a TLR2 to a TLR4 agonist, we chose to test standard E. coli K12 LPS against LPS from P. gingivalis (the etiological agent of periodontal disease)." (PMID 23382974, 2013). "The TLR4 pathway plays a major role in the progression of periodontal diseases." (PMID 36246974, 2022). "Both TLR2 and TLR4 are largely involved in progression of periodontal disease." (PMID 29582430, 2018). "Contrasting these studies, in a cohort of Turkish individuals it was reported that neither TLR2, nor TLR4 polymorphisms were able to distinguish periodontal disease." (PMID 29621153, 2018). "Thus, moesin may play an important role in innate immune responses and TLR4-mediated pattern recognition in periodontal diseases." (PMID 36119109, 2022). "In addition to TLR2 and TLR4, other TLR associations to periodontal disease have been investigated." (PMID 29621153, 2018). "For practical reasons, we arbitrarily selected only two gram-negative microorganisms associated with periodontal disease: due to their distinct potencies in activating TLR2/TLR4 and also because of the distinct virulence factors expressed by these bacteria (e.g., leucotoxin)." (PMID 28114408, 2017). "Toll-like receptors (TLR-2 and TLR-4) and tumor necrosis factor-alpha (TNF-α) are key mediators of immune signaling and tissue breakdown, making them potential biomarkers of periodontal disease activity." (PMID 42154854, 2026). "ROC curve analysis indicated that TLR4 had higher specificity and sensitivity than TLR2 in diagnosing periodontal disease." (PMID 40371381, 2025). "Suppression of TLR4, NF-kB, and IFN pathways and modulating expression of proinflammatory cytokines give way to further exploring the anti-inflammatory effects of statins in periodontal disease." (PMID 37566040, 2023). "In conclusion, the findings presented in this paper demonstrated the cell-mediated anti-inflammatory activity of SAGE in the treatment of chronic inflammatory diseases such as periodontal disease, is mediated at least in part through TLR-2 and TLR-4 signaling pathway." (PMID 34481488, 2021). "This prospective, non-randomized interventional study evaluated TLR-2, TLR-4, and TNF-α levels in gingival crevicular fluid (GCF) for periodontal disease monitoring and assessed the effects of nonsurgical periodontal therapy (NSPT) on clinical parameters." (PMID 42154854, 2026).
esophageal cancer (27 papers, 2014 to 2025). A primary or metastatic malignant neoplasm involving the esophagus. "This indicates that the TLR4/Myd88/NF-κB signaling pathway is involved in esophageal cancer disease progression and is closely associated with LPS." (PMID 38834834, 2024). "For example, Porphyromonas promotes cell proliferation or inflammatory responses via interaction with TLR2 or TLR4 in preclinical models, and is associated with the prognosis of lung or esophageal cancer." (PMID 38304032, 2023). "In this study, our results demonstrated that TLR4 rs1927914 A>G genetic polymorphism contributed to a reduced risk of esophageal cancer." (PMID 33585082, 2021). "This study aims to analyze the association of potential functional genetic polymorphisms in TLR4 with the risk of esophageal cancer." (PMID 33585082, 2021). "Toll-like receptor 4 (TLR4), as a key regulator of both innate and acquired immunity, has been linked with the development of various cancers, including esophageal cancer." (PMID 33585082, 2021). "In this study, the findings showed that the activity of the TLR4/NF-κB signaling pathway was closely associated with the radiosensitivity of esophageal cancer." (PMID 25225511, 2014). "This indicates that EMT progression in mouse esophageal cancer may be associated with the TLR4/Myd88/NF-κB signaling pathway." (PMID 38834834, 2024). "A recent in silico study reported that benzopyrene has a high affinity for Toll-like receptor 4, which is present in human esophageal epithelial cells, and may cause esophageal cancer." (PMID 37402413, 2023). "We also found that the oligonucleotide probe with TLR4 rs1927914G could bind with the nuclear extract from esophageal cancer cells using EMSA; however, that with rs1927914A allele couldn’t." (PMID 33585082, 2021). "Better understanding of the mechanisms underlying TLR4-dependent tumor formation and progression may be useful for therapy of esophageal cancer." (PMID 27323819, 2016). "The TLR4 polymorphism might serve as a biomarker for evaluation of esophageal cancer risk." (PMID 33585082, 2021). "For example, in esophageal cancer, increased expression of TLR3, TLR4, TLR7, and TLR9 has been linked to esophageal squamous cell carcinomas, while TLR1, TLR2, TLR4, and TLR6 are often overexpressed in esophageal adenocarcinoma." (PMID 40109582, 2025). "In esophageal cancer TLR3 was associated with invasion and lymph node metastasis, TLR4 with lymph node metastasis and TLR7 with worse histological grade." (PMID 38709790, 2024). "With regard to esophageal cancer cells, it has been shown that activation of TLR4 stimulates cell proliferation through the TLR4-MyD88-TRAF6-NF-κB signaling pathway, and the inhibition of NF-κB leads to the inhibition of proliferation." (PMID 36840233, 2023). "With respect to esophageal cancer cells, it has been shown that TLR4 activation stimulates cell proliferation via the TLR4-MyD88-TRAF6-NF-κB signaling pathway and that inhibition of NF-κB leads to inhibition of proliferation." (PMID 34444754, 2021). "Rosiglitazone activation of PPARγ suppressed proliferation and induced apoptosis of esophageal cancer cells by inhibiting TLR4-dependent MAPK pathway." (PMID 31011554, 2019). "PPARG is reported to function as an oncogene in ESCC and the activation of PPARG suppresses cell proliferation and induces cell apoptosis of esophageal cancer cells by inhibiting the TLR‐4 dependent mitogen‐activated protein kinase pathway." (PMID 28904855, 2017). "We deduced that PPARγ agonist RGZ inhibited progression of esophageal cancer cells via blocking TLR4 pathway in our system." (PMID 27323819, 2016). "The stimulation of TLR4 with lipopolysaccharide (LPS, a ligand for TLR4) has been revealed to enhance migratory and adhesive properties of esophageal cancer cells." (PMID 27323819, 2016).
esophageal cancer (continued). "In general, our data suggested that activation of PPARγ suppressed proliferation and induced apoptosis of esophageal cancer cells by inhibiting TLR4-dependent MAPK pathway." (PMID 27323819, 2016). "In conclusion, our data suggested that activation of PPARγ suppressed proliferation and induced apoptosis of esophageal cancer cells by inhibiting TLR4-dependent MAPK pathway." (PMID 27323819, 2016). "Taken together, these data suggest that activation of PPARγ inhibits proliferation and induces apoptosis of esophageal cancer cells by inhibiting TLR4-dependent MAPK pathway." (PMID 27323819, 2016). "Collectively, these results indicate that PPARγ agonist inhibits TLR4 signaling in esophageal cancer cells." (PMID 27323819, 2016). "Explore whether Oridonin (Ori) improves esophageal cancer by interfering in the TLR4/NF-κB/NLRP3 inflammasome." (PMID 40606986, 2025). "For example, this study only conducted pharmacological experiments and did not conduct in vivo knockdown or overexpression bidirectional validation of the intervention effect of Ori on TLR4/NF-κB/NLRP3 in esophageal cancer mice, as well as its downstream effects." (PMID 40606986, 2025). "The results of this study indicate significantly increased protein expression of key nodes of the TLR4/Myd88/NF-κB pathway in the esophagus of mice modeled for esophageal cancer in situ, and the same changes in protein expression were observed in esophageal cancer cells after LPS treatment in vitro." (PMID 38834834, 2024). "Similarly, in an esophageal cancer study, it was identified that LPS exacerbates the invasive and migratory behaviors of esophageal cancer cells through the TLR4/NF-κB axis." (PMID 39421736, 2024). "Emerging evidence indicates that TLR4 is overexpressed on multiple types of cancer, and plays a crucial role in carcinogenesis, metastasis and cancer development, whereas the role of TLRs in esophageal cancer has been studied sparsely." (PMID 27323819, 2016). "However, genetic up-regulation of CD14, a co-receptor of TLR4, was observed in families with history of esophageal cancer." (PMID 24847326, 2014). "Therefore, Parabacteroides may exert anticancer activity in esophageal cancer via the suppression of TLR4 and AKT signaling." (PMID 38280026, 2024). "In esophageal cancer cells, PPARG activation by rosiglitazone led to suppressed proliferation and induced apoptosis through the inhibition of the Toll-like receptor 4 (TLR4)-dependent MAPK pathway." (PMID 40564064, 2025). "In esophageal cancer cells, PPARG signaling activation inhibited proliferation and induced apoptosis by inhibiting TLR4-dependent MAPK signaling." (PMID 36114448, 2022). "MAPK has a TLR-4- inducible pathway, therefore it is highly possible that interfering with the TLR-4 and as a result MAPK pathways can effectively prevent the proliferation and also trigger the apoptosis of esophageal cancer cells." (PMID 31011554, 2019). "We also suggested that MAPK activation was regulated by the TLR4 pathway and that blocking the TLR4 and MAPK pathways significantly suppressed proliferation and induced apoptosis of esophageal cancer cells." (PMID 27323819, 2016). "PPARγ activation also inactivated the TLR4 and ERK, JNK, and p38 MAPK pathways in esophageal cancer cells." (PMID 27323819, 2016). "This research highlighted that ERK, JNK, and p38 MAPK activation was regulated by TLR4 pathway, and that inhibition of TLR4, MyD88, ERK, JNK, and p38 attenuated proliferation and induced apoptosis esophageal cancer cells in vitro." (PMID 27323819, 2016). "The aim of the present study is to illuminate the signaling network which orchestrates the regulation of TLR4 and MAPK pathway by PPARγ activation in esophageal cancer cells." (PMID 27323819, 2016). "This study provides evidence indicating that Ori may inhibit inflammatory response by inhibiting TLR4/NF-κB/NLRP3 inflammasome activation, ultimately exert anti esophageal cancer effects." (PMID 40606986, 2025).
esophageal cancer (continued). "Additionally, in vitro experiments revealed that LPS from Bacteroides fragile promoted esophageal cancer cell proliferation, migration, and invasion, and induced EMT by activating the TLR4/Myd88/NF-κB pathway." (PMID 38834834, 2024). "Mechanically, CEH activated TLR4 and MYD88 innate immune signaling, which is advantageous for the activation of the host's innate immunity, for a balanced intestinal environment as well as to exert a chemotherapeutic response to esophageal cancer." (PMID 31293986, 2019). "Mechanically, CEH activated TLR4 and MYD88 innate immune signaling, which is advantageous for the activation of the host's innate immunity to exert a balanced intestinal environment as well as to trigger a better chemotherapeutic response to esophageal cancer." (PMID 31293986, 2019). "Moreover, patients with esophageal cancer and lymph node metastases had higher TLR-4 levels in tumor tissues, and in the subgroup with esophageal-gastric junction adenocarcinoma, significantly higher expression of TLR-7 mRNA and TLR-4, TLR-7, and TLR-9 proteins was observed." (PMID 39451226, 2024).